PSPH (phosphoserine phosphatase)
Diseases named in the same sentence as PSPH in open-access papers (continued):
Sharing a sentence is not in itself a finding about the gene and the disease.
cancer (continued). "The expression of PHGDH (p < 0.001), PSAT1 (p = 0.001), PSPH (p = 0.008), tumoral SHMT1 (p < 0.001), and stromal SHMT1 (p < 0.001) was different according to cancer subtype." (PMID 27277113, 2016). "PSPH and SHMT1 expression in the tumor stroma of HER-2-type cancers was the highest, but the luminal-A tissues showed the lowest expression (p<0.001)." (PMID 24979213, 2014). "Of these we identified a poorly characterized transcript with a region of homology to phospho serine phosphatase (PSPH) and designated phospho serine phosphatase like (PSPHL) as the most differentially over-expressed gene in cancers from African-Americans." (PMID 22783543, 2012). "We identified a robust upregulation of GLUT1 (SLC2A1), a key rate-limiting factor in the transport of glucose in cancer cells, and genes involved in central glucose metabolism (HK2, ENO1, PKM, and LDHA), PPP (G6PD), and de novo serine biosynthesis pathway (PSAT1, PSPH, and SHMT2)." (PMID 40371988, 2025). "Under hypoxic conditions, serine synthesis is driven by three enzymes—phosphoglycerate dehydrogenase (PHGDH), phosphoserine aminotransferase (PSAT), and phosphoserine phosphatase (PSPH)—whose expression is induced by HIF-1α and is crucial for cancer cell proliferation." (PMID 40813760, 2025). "Similarly, the significantly downregulated genes included CHAC1, SLC7A11, PYCR1, PSPH, and DDIT4, among others, with these genes being involved in iron death, cancer cell expansion, and apoptosis (15, –, 19)." (PMID 38299864, 2024). "In metabolically active cancer cells these processes are often dysregulated through oncogenic activity by enzymes such as Phosphoglycerate Dehydrogenase (PHGDH), Phosphoserine Aminotransferase 1 (PSAT-1) and Phosphoserine Phosphatase (PSPH)." (PMID 38702616, 2024). "Our data revealed an increase in serine and related metabolites, along with an increased expression of serine/folate transporters in undifferentiated cancer, but there was no increase in expression of SSP-related genes, such as PHGDH, PSPH, and PSAT1, compared to differentiated cancer." (PMID 38331894, 2024). "The WGCNA on DEFs of paired NSCLCs revealed association of low tumour folate with increased transcripts of GLUT1/4, PHGDH, PSPH, and PSAT1 in NSCLCs, suggesting increased glucose uptake and enhanced glycolytic SSP pathways to contribute cancer serine levels under folate-deficit condition." (PMID 36615660, 2022). "The following genes displayed LOH in at least one cancer: UACA, TWSG1, PSPH, and ZNF490." (PMID 24146633, 2013). "Studies have shown that in the absence of amino acids, cancer cells induce the expression of PHGDH, PSAT1, and PSPH in a GCN2-ATF4-dependent manner to produce sufficient amino acids." (PMID 37147729, 2023).
tumor (48 papers, 2010 to 2026). "Glycine and serine metabolism are frequently upregulated, especially in tumors with EGFR and Phosphoserine Phosphatase (PSPH) mutations, sustaining tumor growth, migration, and immune evasion." (PMID 40775789, 2025). "Expression of stromal PSPH was associated with higher T staging (p = 0.048), whereas expression of tumor GLDC was associated with lower T staging (p = 0.008) and lower Ki-67 LI (p = 0.008)." (PMID 24979213, 2014). "Abnormal expression of PHGDH and PSPH may enhance serine synthesis in tumor cells, positioning them as potential diagnostic biomarkers." (PMID 40265021, 2025). "The neoantigen candidates arising from the PSPH: c.275+1del splice variant are predicted to be likely benign, but this mutation has been observed as a somatic mutation in several patients with tumor (cBioPortal), suggesting its potential relevance in tumor cells." (PMID 41312385, 2025). "The results showed that PSAT1 and PSPH were consistently upregulated in tumour tissues in five GEO datasets, while PHGDH, SLC1A4 and SLC38A5 were upregulated in four datasets." (PMID 40660426, 2025). "In the serine synthesis pathway, key enzymes like PHGDH and PSPH are upregulated in specific tumor types." (PMID 40265021, 2025). "In melanoma, PSPH upregulation promotes tumor growth in vitro and in vivo, whereas its knockdown suppresses proliferation." (PMID 40265021, 2025). "Loss of LKB1 in mutant KRASG12D tumor cells modulates the expression of PSAT1 and PSPH in an mTOR-dependent manner." (PMID 37187454, 2023). "For two of these genes, CRYBB2 and PSPH, expression levels were not only different in tumor epithelium but benign stroma as well." (PMID 36833598, 2023). "Follow-up studies from CBCS found associations between higher expression of PSPH and risk of recurrence (HR 1.76, 95% CI 1.15–2.68) and that both CRYBB2 and CRYBB2P1 promote tumor progression in vivo." (PMID 36833598, 2023). "Nevertheless, PSPH mRNA expression was 1.7-fold elevated in the 50% of NEPC tumours with the highest NKX2–1 expression versus the 50% with the lowest NKX2–1 expression." (PMID 36932191, 2023). "Since we have already shown that PSPH expression significantly contributed to the patients’ poor survival and tumour cell progression, we then explored the potential mechanisms of PSPH in NB." (PMID 36092735, 2022). "PSPH is also an upregulated oncogene in NSCLC that regulates tumor progression and correlates with the clinical stage and pathological features." (PMID 36699468, 2022). "This analysis indicated that both IKBKE and PSAT1, similarly to PHGDH and PSPH, are significantly upregulated in an ER‐negative Pam50:basal subpopulation of tumours, with the highest proliferation index." (PMID 32783398, 2020). "As unlimited growth, invasion, and metastasis are hallmarks of tumor malignancy, we explored the role of PSPH in human NSCLC progression using a transient transfection strategy." (PMID 30977310, 2019). "Quantitative real‐time PCR and Western blot were used to assess PSPH expression in paired tumor and corresponding adjacent non‐tumorous tissues." (PMID 30977310, 2019). "BRAFV600E mutant cells have higher PHGDH, PSAT1, PSPH, tumor SHMT1, and interstitial SHMT1 and GLDC expression than non-mutant cells." (PMID 31423225, 2019). "Serine biosynthesis is also elevated in tumor lysates, where PSPH acts as a rate-limiting enzyme of this pathway; this finding is indicative of its regulatory role in tumor progression." (PMID 26179909, 2015). "High levels of PHGDH, PSPH, SHMT1 in tumor and PSPH in tumor stroma were correlated with high histological grading (p<0.001), ER negativity (p<0.001), PR negativity (p<0.001), and high Ki-67 LI (p<0.001)." (PMID 24979213, 2014). "Altogether, PSPH might be a potential target in reversing immune escape and provide new insights into understanding the function of PSPH expression in NB prognosis and tumor immunology." (PMID 36092735, 2022). "In multiple cancers, PSPH promotes tumor growth and metastasis." (PMID 36467068, 2022).
tumor (continued). "However, high expression of PHGDH, PSAT1, and PSPH is ubiquitous in tumor cells, which activates endogenous serine metabolism and thus weakens the effect of serine starvation on tumor treatment." (PMID 36699468, 2022). "Anti-PSPH polyclonal antibody was applied in the nine tumor cell lines." (PMID 31057610, 2019). "Expression of PHGDH, PSAT1, PSPH and tumor SHMT1 is higher in PDTC and PTC, but lower in MTC." (PMID 31423225, 2019). "The expression of PSPH, tumor SHMT1 and matrix SHMT1 was higher in PTC than FTC." (PMID 31423225, 2019). "Therefore, we next performed dual immunofluorescence staining to determine the paired expression of PHGDH and PSAT, or PHGDH and PSPH in tumor cell monolayers." (PMID 29925909, 2018). "We previously demonstrated that PHGDH and PSPH catalyze the conversion of 3- phosphoglycerate to serine, leading us to assess Phgdh and Psph mRNA and protein levels in LK, B lymphocytes, plasma cells, T lymphocytes, erythroid cells, and BMSCs isolated from the BM of tumor-bearing 5TGM1 mice." (PMID 37055385, 2023). "We hypothesized that PSPH regulating serine-dependent pathways were affected in the TME, and this phenomenon could affect T cell phenotypic states which are linked to the inability of the host to control tumor progression." (PMID 36092735, 2022). "The PSPH expression level was significantly associated with clinicopathological features, including lymph node and distal metastasis (P = 0.010) and advanced tumor node metastasis (TNM) stages (P = 0.0003), but not with age, gender, pathological type, differentiation, or tumor size." (PMID 30977310, 2019). "PSPH was shown to be overexpressed in HCC, promoting the SSP and modulating the immune response to these tumours by attracting tumour supporting monocytes/macrophages while limiting T-cell recruitment." (PMID 38698089, 2024). "Functional assays demonstrated that two miRNAs acted as tumor-suppressive miRNAs in BC cells by targeting cell-cycle-related genes (e.g., TRIP13, CCNB1, RAD51, PSPH, CENPN, KPNA2, and MXRA5)." (PMID 39728605, 2024). "The expression of PSPH and SHMT2 was significantly higher in tumour tissues, whereas PHGDH and PSAT1 were reduced." (PMID 36110969, 2022). "Differential expression of seven of these genes (CFD, ALDH18A1, CHKA, DDIT3, ITGA6, PSPH and SQLE) was replicated in another set of 12 paired NASH-HCCs and adjacent non-tumor livers by RT-qPCR (all P < 0.05 by paired t test)." (PMID 30367044, 2018). "Mechanisms whereby tumours sustained HT under CD44-knockdown conditions include upregulation of PHGDH, PSAT1 and PSPH that drove glycolysis-dependent activation of serine/glycine-cleavage systems to provide one-methyl group for HT synthesis." (PMID 29674746, 2018). "In contrast, HUH7 cells showed a higher expression of 98 metabolic targets upregulated in tumours (e.g. HK2, PKM, PSPH, GLUL, ASNS, and fatty acid synthesis enzymes ACLY, FASN)." (PMID 30176945, 2018). "Eight genes centromeric to SEPT14 (ZNF713, MRPS17, GBAS, PSPH, CCT6A, SUMF2, PHKG1 and CHCHD2) were amplified in tumour 4 only." (PMID 21170331, 2010). "As previously noted, NSCLC patient tumor samples showed higher expression of the different enzymes of the de novo ser/gly synthesis pathway, i.e. PHGDH, PSAT1, PSPH and SHMT2, compared to the adjacent normal lung tissue, which hardly showed any expression of ser/gly pathway enzymes." (PMID 38160212, 2024). "Interestingly, the expression of these genes increases with tumor staging of NSCLC (p < 0.0001 for PSAT1, PSPH and SHMT2)." (PMID 38160212, 2024). "In serine/glycine metabolism, tumor cells synthesize and utilize serine/glycine by a phosphoglycerate dehydrogenase (PHGDH)/phosphoserine aminotransferase 1 (PSAT1)/phosphoserine phosphatase (PSPH)/hydroxymethyltransferase (SHMT)-mediated continuous enzymatic reaction." (PMID 36778122, 2023).
tumor (continued). "To assess the clinical relevance of targeting the SSP in CRC for radiosensitizing purposes, we first examined mRNA levels of PHGDH, PSAT1 and PSPH in patient-derived data from normal tissues (TCGA Target GTEx) and CRC tumor tissues (TCGA COAD study) using the online Xena Explorer tool." (PMID 36291844, 2022). "A-485 and B029-2 are two selective and highly potent p300 inhibitors that suppress tumor cell metabolism and tumor progression by targeting p300/CBP and reducing the levels of key metabolic enzyme genes, such as PSPH, PSAT1 promoter region H3K18Ac, and H3K27Ac." (PMID 36699468, 2022). "Moreover, downregulating the rate-limiting enzymes of serine/glycine metabolism, such as phosphoserine phosphatase (PSPH) and phosphoserine aminotransferase 1 (PSAT1), may disrupt the pro-tumor effects mediated by serine/glycine metabolism." (PMID 40265021, 2025). "In addition, PSAT1 and PSPH, which catalyze the final and irreversible step of serine synthesis, promote tumor metastasis independent of their serine synthase activity." (PMID 37187454, 2023).
infection (7 papers, 2018 to 2023). The state of being infected such as from the introduction of a foreign agent such as serum, vaccine, antigenic substance or organism. "In glycine, serine, and threonine metabolism, the expression of PHGDH, phosphoserine aminotransferase (PSAT) and PSPH, which converted the glycolytic intermediate 3-phosphoglycerate (3-PG) to serine, were activated after infection." (PMID 37358285, 2023). "In our study, all genes encoding these proteins increased their expression due to infection with ncp strains PHGDH (0.99; 1.82), PSAT-1 (0.64; 1.28), and PSPH (1.09; 2.17), and the increase in PSPH expression was confirmed by the RT-qPCR test." (PMID 35746747, 2022). "After DnCPV-23 infection, the expression levels of the phosphoserine phosphatase genes were significantly higher in the DnCPV-23-infected midgut than in the non-infected group, suggesting that serine metabolism disorders were induced after DnCPV-23 infection." (PMID 36499611, 2022). "PHGDH and PSPH also increased their expression due to infection with the cp strain." (PMID 35746747, 2022). "In our study, the expression levels of the phosphoserine phosphatase genes were significantly higher in DnCPV-23-infected midgut than in the non-infected group, suggesting that serine metabolism disorders were induced after DnCPV-23 infection." (PMID 34906167, 2021). "However, the proteins SAL1 phosphatase-like, phosphatidylinositol-bisphosphatase, phosphoserine phosphatase, phosphoglycerate mutase, 2-isopropylmalate synthase, and fructose-bisphosphate aldolase were down-regulated by infection stress." (PMID 30482156, 2018).
PSPH also shares sentences with these, for which no sentence is quoted: thyroid cancer (3 papers); serine deficiency (2); acute myeloid leukemia (1); adenocarcinoma (1); Alzheimer disease (1); bladder cancer (1); brain malformations (1); brain tumors (1); Diamond-Blackfan anaemia (1); Ewing sarcoma (1); head and neck cancer (1); lacrimal gland adenoid cystic carcinoma (1); metabolism disorders (1); microcephaly (1); nasopharyngitis (1); pancreatic cancer (1); pancreatitis (1); peripheral neuropathy (1); phosphoserine phosphatase deficiency (1); phyllodes tumor (1); Psoriasiform dermatitis (1); renal carcinoma (1); sarcopenia (1); triple-negative breast carcinoma (1).